SYNE2 (spectrin repeat containing nuclear envelope protein 2)
Diseases named in the same sentence as SYNE2 in open-access papers:
SYNE2 is named in the same sentence as 69 diseases in open-access papers, as found by Europe PMC text mining. Sharing a sentence is not in itself a finding about the gene and the disease. The quoted sentences say what the papers report.
Emery-Dreifuss muscular dystrophy (15 papers, 2013 to 2024). Emery-Dreifuss muscular dystrophy (EDMD) is characterized by muscular weakness and atrophy, with early joint contractures and cardiomyopathy. "SYNE2 encodes the Nesprin protein 2 that is associated with laminopathies in human, most notably the Emery-Dreifuss muscular dystrophy." (PMID 37919601, 2024). "Gene SYNE2 is linked to Emery-Dreifuss muscular dystrophy (#612999) and its clinical manifestations of proximal muscle weakness, as well as cardiac involvements such as arrhythmias, dilated cardiomyopathy, or heart failure." (PMID 35910219, 2022). "ResponseNet also suggested that a problem in the SYNE2 gene, which is known to cause Emery Dreifuss muscular dystrophy, leads to the loss of miR-29 by affecting the MYC transcription regulation complex." (PMID 31114913, 2019). "Heterozygous variants affecting SYNE2 cause autosomal dominant Emery-Dreifuss muscular dystrophy 5 (MIM#612999)." (PMID 31014393, 2019). "In human, mutations in the SYNE2 gene cause Emery-Dreifuss muscular dystrophy (EDMD) 5, an autosomal dominant disease." (PMID 30220251, 2018). "Syne2 – The SYNE genes encoding nesprin proteins have been directly linked to Emery-Dreifuss muscular dystrophy." (PMID 29912636, 2018). "Other structural proteins (e.g., SYNE1 and SYNE2) also cause an Emery-Dreifuss muscular dystrophy phenotype (EDMD type 3)." (PMID 29750601, 2018). "No inborn errors of metabolism, neuromuscular junction conditions, or myopathies were found to explain the patient's recurrent rhabdomyolysis except for two variants of unknown significance in the SYNE2 gene that has been linked with Emery-Dreifuss muscular dystrophy." (PMID 39497864, 2024). "SYNE2 mutations have been associated with skeletal and cardiac muscle diseases, including Emery-Dreifuss muscular dystrophy (EDMD)." (PMID 40757551, 2024). "In musculoskeletal and cardiac diseases, SYNE1 and SYNE2 mutations had been associated with Autosomal-Dominant Emery-Dreifuss Muscular Dystrophy (AD-EDMD) and EDMD-like phenotypes." (PMID 30245638, 2018). "Emery-Dreifuss muscular dystrophy (EDMD) was initially linked to mutations in the EMD gene, which encodes the INM protein emerin, but can also be caused by mutations in LMNA and NE genes SYNE1, SYNE2 and TMEM43." (PMID 24490688, 2014).
cardiomyopathy (9 papers, 2014 to 2024). A disease of the heart muscle or myocardium proper. "Targeting of the Syne2 region near the C-terminus in combination with loss of Syne1 C-terminal isoforms in a cardiomyocyte specific fashion led to early onset cardiomyopathy." (PMID 30220251, 2018). "The nesprin-2 encoding gene SYNE2 has also been reported in patients with cardiomyopathy phenotype and inheritance status of multiple variants of unknown significance." (PMID 33567613, 2021). "It is worth noting that the combination of the heterozygous variants in CAP2, ADCY6, and SYNE2, associated with the loss of function in TPM2, could also be related to cardiomyopathy." (PMID 37744435, 2023). "The regulatory roles of other enriched genes in cardiomyopathy networks (including SYNE2, APOB, XIRP1, ALPK3, and LRPPRC) are not clear." (PMID 34236536, 2021).
laminopathies (5 papers, 2013 to 2024). "Dysregulation of genes involved in organizing and maintaining nuclear structures, such as SYNE1, SYNE2, TREM43, EMD and LMNA is frequently associated with diverse diseases termed laminopathies, which often affect the muscle tissue." (PMID 25906157, 2015).
melanoma (4 papers, 2018 to 2021). A malignant, usually aggressive tumor composed of atypical, neoplastic melanocytes. "In a bivariate analysis combining the nevus results with a recent melanoma GWAS meta-analysis (12,874 cases, 23,203 controls), SNPs near GPRC5A, CYP1B1, PPARGC1B, HDAC4, FAM208B, DOCK8, and SYNE2 reached global significance, and other loci, including MIR146A and OBFC1, reached a suggestive level." (PMID 30429480, 2018). "We have highlighted eight novel loci, including the genes HDAC4, SYNE2, and most notably GPRC5A, where quite large samples of melanoma cases or nevus count were not sufficiently powerful to reach formal genome-wide significance in univariate analyses, but the combined evidence is conclusive." (PMID 30429480, 2018).
pancreatic ductal adenocarcinoma (4 papers, 2020 to 2023). An infiltrating adenocarcinoma that arises from the epithelial cells of the pancreas. "It was reported that the knockdown of SYNE2 in pancreatic ductal adenocarcinoma cells reduced their invasive activities and survival." (PMID 36014414, 2022). "In pancreatic ductal adenocarcinoma, SNORA23, an H/ACA-box type small nucleolar non-coding RNA participating on pseudouridylation, was found upregulated and associated with metastasis formation by increasing the expression of spectrin repeat-containing nuclear envelope 2 (SYNE2)." (PMID 37369946, 2023).
atrial fibrillation (3 papers, 2013 to 2023). A disorder characterized by an electrocardiographic finding of a supraventricular arrhythmia characterized by the replacement of consistent P waves by rapid oscillations or fibrillatory waves that vary in size, shape and timing and are accompanied by an irregular ventricular response. "ZFHX3 was identified as a crucial risk factor for atrial fibrillation, and SYNE2 contributed to atrial fibrillation." (PMID 35924220, 2022). "ZFHX3 was identified as a crucial risk factor for atrial fibrillation, SYNE2 contributed to cardiac arrhythmia, and GJD3 caused abnormal atrioventricular node conduction." (PMID 35924220, 2022).
Intellectual disability (3 papers, 2021 to 2024). "This cardinal role in neurogenesis and/or regulation of Wnt-signalling may be underlying the previously suggested association of SYNE2 with ASD or intellectual disability." (PMID 34573277, 2021). "Collectively, these data provide novel insights into the cardinal role of the nesprin-2 giant in neurodevelopment and suggest that the biallelic hypomorphic SYNE2 mutations may be a new cause of intellectual disability and ASD." (PMID 34573277, 2021). "The compound heterozygous variants of SYNE2 (NM_182914.3:c.2483T>G; p.(Val828Gly) and NM_182914.3:c.2362G>A; p.(Glu788Lys)) were identified in a 4.5-year-old male, clinically diagnosed with autism spectrum disorder, developmental delay and intellectual disability." (PMID 34573277, 2021). "We have identified novel compound heterozygous missense variations in SYNE2, which consequently reduce the amount of nesprin-2 giant and thus, hypomorphic variations as the cause of ASD and intellectual disability." (PMID 34573277, 2021). "Remarkably, biallelic heterozygous missense SYNE2 mutations in the spectrin repeat domain of Nesprin-2 giant were recently identified in a patient clinically diagnosed with ASD, along with developmental delay and intellectual disability." (PMID 39519078, 2024). "SYNE2 variations may affect SYNE1 functions, which has already been associated with intellectual disability and ASD." (PMID 34573277, 2021).
muscular dystrophies (3 papers, 2018 to 2022). "Spectrin repeat containing nuclear envelope protein 2, SYNE2, a nuclear outer membrane protein that binds cytoplasmic F-actin, is associated with muscular dystrophies and colorectal cancer." (PMID 33097818, 2020).
Alzheimer disease (2 papers, 2021 to 2024). A progressive, neurodegenerative disease characterized by loss of function and death of nerve cells in several areas of the brain leading to loss of cognitive function such as memory and language. "The three top hits, HO-1 (heme oxygenase-1), MIOS, and SYNE2, exert diverse functions, yet each has been linked to neurodegeneration and Alzheimer’s disease." (PMID 37919601, 2024).
autism (2 papers, 2021 to 2024). Persistent deficits in social interaction and communication and interaction as well as a markedly restricted repertoire of activity and interest as well as repetitive patterns of behavior. "Identifying additional SYNE1 and/or SYNE2 mutations that show associations or direct involvement in autism will aid to elucidate the underpinned molecular mechanisms." (PMID 34573277, 2021).
developmental delay (2 papers, 2021 to 2024). "Here, we describe a patient manifesting autism spectrum disorder (ASD) and developmental delay; whole-exome sequencing revealed compound heterozygous mutations in SYNE2." (PMID 34573277, 2021).
hepatocellular carcinoma (2 papers, 2016 to 2019). A malignant tumor that arises from hepatocytes. "Variants of SYNE2 have been associated with p21 expression and reduced overall survival in hepatitis B-related hepatocellular carcinoma." (PMID 30913233, 2019).
pancreatic cancer (2 papers, 2018 to 2022). "Moreover, the expression of some proteins that are associated with the progression of pancreatic cancer, such as SYNE2, ICMT, and FAM172A, is regulated by HCQ." (PMID 36014414, 2022). "SYNE2 (nesprin-2), an actin-binding nuclear envelope protein that tethers the nucleus to the cytoskeleton, has been shown to promote pancreatic cancer metastasis." (PMID 30022044, 2018). "Interestingly, our results showed that the expression of protein SYNE2 and ICMT was decreased after HCQ treatment, suggesting that HCQ may inhibit the proliferation of pancreatic cancer cells by reducing the expression of SYNE2 and ICMT." (PMID 36014414, 2022). "Furthermore, HCQ may prevent the progression of pancreatic cancer by regulating the expression of nesprin-2 (SYNE2), protein-S-isoprenylcysteine O-methyltransferase (ICMT), and cotranscriptional regulator FAM172A (FAM172A)." (PMID 36014414, 2022). "It was reported that the knockdown of SYNE2 or suppression of ICMT could inhibit the proliferation and invasion of pancreatic cancer." (PMID 36014414, 2022).
adenoma (1 paper, 2020). A neoplasm arising from the epithelium. "Since high‐risk adenomas are characterized by chromosomal gains and losses, the up‐regulation of SYNE2 might be linked to these DNA aberrations." (PMID 31784980, 2020). "Next to Hp, LAMP1, SYNE2, and ANXA6 were selected in the analysis for high‐risk adenomas, and also LRG1, RBP4, and FN1 for the high‐risk adenomas and CRCs." (PMID 31784980, 2020). "We conclude that Hp, LAMP1, SYNE2, LRG1, RBP4, FN1, and ANXA6 may be of value as stool biomarkers for early detection of high‐risk adenomas and CRCs." (PMID 31784980, 2020). "We identified a biomarker panel of Hp, LAMP1, SYNE2, and ANXA6 for identification of high‐risk adenomas and two biomarker panels – Hp and LRG1, as well as Hp, LRG1, RBP4, and FN1 – for identification of high‐risk adenomas and CRCs that outperformed hemoglobin." (PMID 31784980, 2020).
autism spectrum disorder (1 paper, 2021). A spectrum of developmental disorders that includes autism, and Asperger syndrome. "In agreement, the current study reports two novel compound heterozygous SYNE2 missense mutations (p.(E788K) and p.(V828G)), which show an association with autism spectrum disorder (ASD)." (PMID 34573277, 2021).
bipolar disorder (1 paper, 2015). A disorder of the brain that causes unusual shifts in mood, energy, activity levels and the ability to carry out day-to-day tasks. "Therefore, future research addressing whether mice that are deficient in Sun1 and/or Sun2, or Syne1 and/or Syne2 show cognition phenotypes such as schizophrenia or bipolar disorder could be beneficial in the field of psychiatric medicine." (PMID 26035387, 2015).
epilepsy (1 paper, 2025). A brain disorder characterized by episodes of abnormally increased neuronal discharge resulting in transient episodes of sensory or motor neurological dysfunction, or psychic dysfunction. "The epilepsy risk gene KCNQ2 was not rescued (avg log2FC −.763 corP < .01), whereas SYNE2 was (corP > .675)." (PMID 40704780, 2025).
hereditary cardiomyopathy (1 paper, 2021). "These genes include VCP, COL6A2, SYNE2, PYGM gene, and TPM2, and they warrant investigation of the more complex interacting mechanism underlying the hereditary cardiomyopathy phenotypic features." (PMID 33567613, 2021).
lung adenocarcinoma (1 paper, 2020). A carcinoma that arises from the lung and is characterized by the presence of malignant glandular epithelial cells. "Moreover, considering the frequent alterations of THSD7B, SYNE2, GRM3, and FLNC in lung squamous cell carcinoma and lung adenocarcinoma, we investigated the applicability of ITS to NSCLC patients treated with ICIs." (PMID 32969604, 2020).
lupus (1 paper, 2021). "Of those, the most notable are Dnajc28, Syne2 (synaptic nuclear envelope 2) that are upregulated in the MRL/lpr model compared with both Fn14ko and MRL/+, as well as transthyretin (Ttr) that is downregulated in the lupus-prone mice compared with both controls." (PMID 34440346, 2021).
Myalgia (1 paper, 2024). "Our findings imply that the novel heterozygous SYNE2 mutation results in a monoallelic splicing defect of nesprin-2, thereby leading to a rare cause of myalgia and hyperCKemia." (PMID 40757551, 2024).
periodontitis (1 paper, 2015). An acute or chronic inflammatory process that affects the tissues that surround and support the teeth. "CD24, EST1, MTSS1, ING3, CCND2 and SYNE2 may have the potential to be used as targets for periodontitis diagnosis and treatment.; however, more research is still needed to validate our findings." (PMID 26705104, 2015). "EST1, MTSS1, ING3, CCND2 and SYNE2, as well as their corresponding miRNAs, might be potential therapeutic targets for periodontitis." (PMID 26705104, 2015).
cancer (14 papers, 2010 to 2024). A tumor composed of atypical neoplastic, often pleomorphic cells that invade other tissues. "SYNE2 (or nesprin 2) is a nuclear envelope protein that is involved in the regulation of nuclear trafficking; even though its role in cancer is yet to be established, there are indications that its presence is pivotal in the DNA damage response." (PMID 31784980, 2020). "Moreover, Nucleolin, n-Myc, Ddx17, and Syne2 participate in cancer progression when overexpressed by altering ribosome biogenesis." (PMID 34848840, 2021). "ACIN1 and SYNE2 showed a combined effect with ESR2 on either OS or DFS in 9 out of 17 cancer types, TNFRSF13C showed a combined effect with ESR2 in 8 cancer types, and MDM4 showed a combined effect with ESR2 in 7 cancer types." (PMID 39201394, 2024). "Most of the candidate genes of which we confirmed cancer-specific AS in NSCLC are also involved in these processes (ADD3, CLSTN1, FN1, MYO18A, NUMB, SYNE2, and TPM1)." (PMID 21118496, 2010). "Almost all variants of SYNE2, ACAN, and PDZD7 genes identified in our patients had not been shown to be of clinical importance with regard to cancer biology." (PMID 35884495, 2022). "In addition to known cancer driver genes such as ERBB2 (6% of cases), NRAS (3%), MET (3%), PIK3CA (1%), AKT2 (1%), TSC1 (1%), and ERBB4 (1%), several putative cancer genes were identified, such as PTPRC, SYNE2, GRIN2A, and CDH10." (PMID 24576404, 2014).
tumor (13 papers, 2015 to 2025). "The SYNE2 is a protein-coding gene, associated with various neoplasms, while another protein-coding gene, the MAP4, is involved in microtubule dynamics and its disruption may lead to mitotic abnormalities." (PMID 40941618, 2025). "Therefore, the ESR2 regulation of SYNE2 expression could be tumor-dependent and requires further functional studies." (PMID 39201394, 2024). "Furthermore, eight target genes (COL4A3, FAM30A, FCRL5, MDM4, SYNE2, TNFRSF13C, TPTEP2, VAMP1) were systematically positively correlated with ESR2 expression patterns in tumor types with low ESR2 expression as a prognostic factor concerning OS or DFS." (PMID 39201394, 2024). "Notably, our findings highlight seven genes (FAM30A, MDM4, POU2AF1, SYNE2, TNFRSF13C, TPTEP2, VAMP1) presenting positive correlations with ESR2 expression patterns in all tumor types with high ESR2 expression as a positive prognostic factor with regard to OS or DFS." (PMID 39201394, 2024). "Finally, we investigated genes displaying similar expression patterns as ESR2 in tumor tissues, identifying potential co-expressed genes that may exert a synergistic effect on clinical outcomes, with significant results, including the expression of ACIN1, SYNE2, TNFRSF13C, and MDM4." (PMID 39201394, 2024).
myopathies (3 papers, 2014 to 2024). "Screening of SYNE1 (nesprin-1), SYNE2 (nesprin-2), and SUN1 and SUN2 genes identified variants in patients with EDMD or related myopathies." (PMID 38831796, 2024).
genetic disorder (1 paper, 2019). "Although mutations in the human EMD gene are most closely tied to the genetic disorder EDMD1, similar phenotypes arise from mutations in genes coding for interacting proteins, such as LMNA, SYNE1, SYNE2, and TMEM43." (PMID 30871242, 2019).
intestinal diseases (1 paper, 2023). "Several of these genes, including Ralbp1, Pfas, Tyro3, Opcml, Syne2, Six4, Tll2, and Slc23a2, were previously implicated in gut microbiome abundance, metabolic traits, and several intestinal diseases." (PMID 37420306, 2023).
muscular disorders (1 paper, 2022). "Moreover, both SYNE1 and SYNE2 have been associated with muscular disorders." (PMID 36409768, 2022).
neurodevelopmental disorder (1 paper, 2021). A behavioral and cognitive disorder with onset during the developmental period that involves impaired or aberrant development of intellectual, motor, or social functions. "Specifically, the disease-causing variants of SYNE2 in 410 trios manifesting neurodevelopmental disorders using whole-exome sequencing were explored." (PMID 34573277, 2021).
SYNE2 also shares sentences with these, for which no sentence is quoted: breast carcinoma (9 papers); Arrhythmia (2); dilated cardiomyopathy (2); nevus (2); ovarian carcinoma (2); progeria (2); amyotrophic lateral sclerosis (1); arthrogryposis multiplex congenita (1); asthma (1); breast tumor (1); cardiac arrhythmia (1); cardiac hypertrophy (1); ciliopathy (1); COVID-19 (1); endometrial tumors (1); endometriosis (1); glioblastoma (1); head and neck cancer (1); heart failure (1); Hypertension (1); hypertrophic cardiomyopathy (1); infection (1); Infertility (1); invasive breast carcinoma (1); ischemia (1); kidney cancer (1); Lissencephaly (1); lung carcinoma (1); lung disease (1); lung squamous cell carcinoma (1).
A further 10 diseases each share a sentence with SYNE2 in 1 paper.